NXPH2 (neurexophilin 2)
Description:
May be signaling molecules that resemble neuropeptides and that act by binding to alpha-neurexins and possibly other receptors.
Synonyms: NPH2
Tractability: Antibody: UniProt places it where antibodies can reach, with high confidence; UniProt predicts a signal peptide or a membrane-spanning region; its Gene Ontology location is reachable by antibodies, with medium confidence.
Gene: Protein-coding gene on chromosome 2 (138,669,157 to 138,780,390, reverse strand). Ensembl gene ENSG00000144227.
Subcellular location: Secreted
Gene Ontology:
Molecular function: signaling receptor binding
Biological process: neuropeptide signaling pathway
Cellular component: extracellular region
Genetic constraint (gnomAD): Loss-of-function variants: 5 observed, 19.74 expected, observed/expected ratio (o/e) 0.25, 90% interval 0.13 to 0.53. The upper end of that interval is the gene's LOEUF score, 0.53, which puts it in group 2 of 6, group 1 being the genes least tolerant of losing a copy. Missense variants: 289 observed, 327.4 expected, observed/expected ratio (o/e) 0.88, 90% interval 0.8 to 0.97. Synonymous variants: 154 observed, 129.25 expected, observed/expected ratio (o/e) 1.19, 90% interval 1.04 to 1.36.
Homologues: Orthologues: chimpanzee NXPH2 (100% identical), macaque NXPH2 (99% identical), guinea pig NXPH2 (98% identical), pig NXPH2 (97% identical), dog NXPH2 (97% identical), mouse Nxph2 (89% identical), rabbit NXPH2 (88% identical), rat Nxph2 (87% identical), tropical clawed frog nxph2 (80% identical), zebrafish nxph2a (66% identical). Paralogues in human: NXPH1 (62% identical), NXPH4 (47% identical), NXPH3 (46% identical).
Diseases named in the same sentence as NXPH2 in open-access papers:
NXPH2 is named in the same sentence as 5 diseases in open-access papers, as found by Europe PMC text mining. Sharing a sentence is not in itself a finding about the gene and the disease. The quoted sentences say what the papers report.
autism (1 paper, 2013). Persistent deficits in social interaction and communication and interaction as well as a markedly restricted repertoire of activity and interest as well as repetitive patterns of behavior. "One SNP with nominal association in family-based samples is in a region previously reported in a rare deletion in a case with autism features – rs4245867 located between NXPH2 and LRP1B." (PMID 24204716, 2013).
epilepsy (1 paper, 2023). A brain disorder characterized by episodes of abnormally increased neuronal discharge resulting in transient episodes of sensory or motor neurological dysfunction, or psychic dysfunction. "Although the biobank and deCODE genetics-specific GWAS did not identify any genome-wide significant loci for GGE or ‘all epilepsy,’ one significant locus at 2q22.1 (nearest gene, NXPH2) emerged for FE." (PMID 37653029, 2023).
pancreatic cancer (1 paper, 2024). "NXPH1 and NXPH2 have been reported to be highly expressed in pancreatic cancer." (PMID 39559360, 2024).
infection (1 paper, 2023). The state of being infected such as from the introduction of a foreign agent such as serum, vaccine, antigenic substance or organism. "Among them, eight DEGs (RF00100, NXPH2, SEC61G, GADD45G, TUBAL3, LIPE, CSRNP1, and FAM20A) were shared across different comparison groups after FX0910 infection." (PMID 37982609, 2023).
NXPH2 also shares sentences with these, for which no sentence is quoted: asthma (1 paper).